CDC42 (cell division cycle 42)
Diseases named in the same sentence as CDC42 in open-access papers (continued):
Sharing a sentence is not in itself a finding about the gene and the disease.
cervical carcinoma (14 papers, 2012 to 2026). A carcinoma arising from either the exocervical squamous epithelium or the endocervical glandular epithelium. "Further Tiam1, a known oncogene is dysregulated in NSCLC, endometrial, colorectal, pancreatic, and cervical cancer and is known to activate both Rac-1 and Cdc42." (PMID 37024613, 2023). "The data above further revealed that HCP5 regulated the miR-216a-5p/CDC42 axis to enhance cervical cancer cell proliferation." (PMID 35399723, 2022). "Above all, HCP5, as an oncogene, can promote proliferation and migration ability of cervical cancer via the regulation of the miR-216a-5p/CDC42 axis." (PMID 35399723, 2022). "The stable cell lines were constructed to explore the effect of HCP5 on the promotion of cervical cancer and the regulatory role on the expression of miR-216a-5p and CDC42." (PMID 35399723, 2022). "In this study, RT-qPCR and western blot demonstrated that lncRNA HCP5 promoted cervical cancer cell line proliferation and migration by inhibiting the expression of miR-216a-5p and resulting in the upregulation of CDC42." (PMID 35399723, 2022). "In conclusion, our results illuminated that HCP5, an oncogenic lncRNA, is overexpressed in cervical cancer, and it can promote tumorigenicity of cervical cancer cells by upregulating CDC42 expression via miR-216a-5p." (PMID 35399723, 2022). "Small GTPases of the Rho family have been studied mainly on cervical cancer cell lines and RhoA, Rac1, and Cdc42 are the best characterized." (PMID 32443784, 2020). "Previous studies have shown that miR-29a was low expression in cervical cancer, as a tumor suppressor, miR-29a can target multiple genes, such as CDC42, HSP47, SIRT1 and DNMT1." (PMID 33150075, 2020). "In this study we analyzed the expression of the GTPases Rac1, RhoA, Cdc42, and the Rho-GEFs, Tiam1 and beta-Pix, in cervical pre-malignant lesions and cervical cancer cell lines." (PMID 22443139, 2012). "Therefore, HCP5/miR-216a-5p/CDC42 axis may serve as an essential promising therapeutic target for the clinical treatment of cervical carcinoma." (PMID 35399723, 2022). "Hence, we hypothesized that HCP5 could compete with miR-216a-5p to upregulate CDC42 expression in cervical cancer." (PMID 35399723, 2022). "RAC1 and CDC42 may be involved in the progression of cervical cancer migration induced by HMGB1." (PMID 30962261, 2019). "RAC1 and CDC42 may involve in the progression of cervical cancer migration as downstream of HMGB1." (PMID 30962261, 2019). "E3 ligase MARCH 7 acts as a tumor-promoting gene in human cervix cancer via interacting with VAV2, triggering the activation of CDC42 and RAC1, i.e., VAV1/RAC1/CDC42 pathway." (PMID 34769401, 2021). "Whether miR-216a-5p and CDC42 are involved in HCP5-induced growth and migration in cervical cancer was further investigated." (PMID 35399723, 2022).
Alzheimer disease (12 papers, 2011 to 2024). A progressive, neurodegenerative disease characterized by loss of function and death of nerve cells in several areas of the brain leading to loss of cognitive function such as memory and language. "Mice with a heterozygous deficiency of Cdc42GAP that encodes CDC42 GTPase-activating protein had impaired cognitive behavior, neuronal senescence, and the pathological phenotypes of Alzheimer's disease." (PMID 38042785, 2023). "A previous study demonstrated that the pathway of RPPH1/miR-330-5p/CDC42 is involved in the compensatory behavior of brain neurons to combat synaptic loss during the pathogenesis of Alzheimer's disease." (PMID 31645843, 2019). "Furthermore, disruption of Cdc42 function in the nervous system has been implicated in Alzheimer’s disease, schizophrenia, epilepsy and neurofibromatoses." (PMID 27482713, 2016). "Regarding clinical practices, a study found that CDC42 is positively correlated with Th2 cells and inversely correlated with Th17 cells in Alzheimer's disease patients." (PMID 37703110, 2023). "Another recent study reports that CDC42 is positively correlated with the MMSE score in Alzheimer's disease patients." (PMID 37703110, 2023). "A large proportion of the identified genes such as CDC42 were also altered in Parkinson’s (PD) and Alzheimer’s disease (AD)." (PMID 34111223, 2021). "For example, in Alzheimer’s disease, there is a significant upregulation of Cdc42 activity." (PMID 39559701, 2024). "Netrin signaling is similarly implicated in synaptogenesis, synaptic plasticity, Alzheimer's disease, schizophrenia, and brain tumor cell biology, suggesting that the significance of netrin-1 signaling via Cdc42 likely extends beyond roles directing chemotropic axon guidance." (PMID 27482713, 2016). "For six of these pathways IPA predicted decreased activity: CDC42 signaling, Sumoylation Pathway, Cell Cycle: G2/M DNA Damage Checkpoint Regulation, Neuroprotective Role of THOP1 in Alzheimer’s Disease, PD-1,PD-L1 cancer immunotherapy pathway and ILK Signaling." (PMID 36016386, 2022). "Moreover, analysis of the GSE48350 dataset confirmed similar changes in HDAC1, CDC42 and YES1 expression in Alzheimer's disease, thereby providing a molecular connection between aging and Alzheimer's disease (AD)." (PMID 30341976, 2018).
Salmonella Infections (12 papers, 2013 to 2025). Infections with bacteria of the genus SALMONELLA. "We find that CDC42 K153 can be deacetylated by the NAD+-dependent deacetylase SIRT2 after Salmonella infection, which causes an impaired binding of its downstream effector PAK4." (PMID 36812247, 2023). "In the AOM/DSS mouse model, lower CDC42 K153 acetylation caused by Salmonella infection is associated with higher PAK1 phosphorylation but lower PAK4 phosphorylation." (PMID 36812247, 2023). "MEK1/2, similar as Cdc42, are enriched around SCVs upon Salmonella infection, whereas it shows cytoplasmic diffused expression in ΔsopB S. Tm infection condition." (PMID 36717589, 2023). "We systematically investigated the role of CDC42 acetylation in CRC and revealed how Salmonella infection regulated CDC42 activity and its downstream signaling pathways through acetylation." (PMID 36812247, 2023). "We then used a Salmonella infection mouse model to investigate the effect of CDC42 K153 acetylation on CRC tumorigenesis." (PMID 36812247, 2023). "In this study, we show that Salmonella infection disturbs acetylation of more than 90 proteins, including Rho GTPase cell division cycle 42 (CDC42)." (PMID 36812247, 2023). "Our data, however, show that activated Cdc42 induces vimentin enrichment around replication vacuoles in Salmonella infection." (PMID 36717589, 2023). "Salmonella infection activates SIRT2 to deacetylate CDC42 K153, reduces cell apoptosis, enhances the migration and invasion abilities of tumor cells, and promotes tumorigenesis." (PMID 36812247, 2023). "For example, Salmonella infection can directly activate CDC42 through the effector protein SopE2 (Salmonella T3SS-1 effector) to promote actin cytoskeleton rearrangement, thereby facilitating its own invasion." (PMID 36812247, 2023). "A previous study showed that Salmonella infection can induce host cell actin rearrangement to promote bacterial internalization by activating CDC42." (PMID 36812247, 2023). "Together with the finding that SopB activates Cdc42, these results suggest that SopB-Cdc42-vimentin signaling axis is critical for maintaining concrete SCV during Salmonella infection." (PMID 36717589, 2023). "Consistently, upon Salmonella infection, increased dispersive SCVs by Cdc42 inhibition or Cdc42-DN were diminished by MEK1/2 activation." (PMID 36717589, 2023). "Rapid degradation of SopE allows the temporal regulation of Cdc42 and Rac activity during Salmonella infection." (PMID 33563785, 2021). "The observed upregulation of miR-124 expression and downregulation of IQGAP2 expression indicated that the CDC42-MAPK pathway is highly possibly inhibited after Salmonella infection." (PMID 31186019, 2019). "CCL4, IL8L1 and CDC42 were contained in the Salmonella infection pathway and were all targeted by miR-34a." (PMID 28086873, 2017). "This particular miRNA was reported in the context of host response to bacterial infections as well as in regulation of actin cytoskeleton and FA proteins such as CDC42, which is an important factor for cellular Salmonella infection." (PMID 23826261, 2013). "RAC1 and CDC42 are major Rho GTPases during cellular Salmonella infection and their activation through Salmonella effector proteins leads to formation of filopodia and uptake of pathogens." (PMID 23826261, 2013). "The result showed that CDC42 WT-, K153Q-, and K153R-overexpressing cells had similar phosphorylation levels of JNK after Salmonella infection, but p38 still had a lower phosphorylation level in CDC42 K153R-overexpressing cells than in CDC42 WT- or CDC42 K153Q-overexpressing cells." (PMID 36812247, 2023). "However, under Salmonella infection condition, acetylation level of CDC42 K153 was correlated to the phosphorylation of p38 instead of JNK." (PMID 36812247, 2023). "We then focused on CDC42 to study the role of acetylation of CDC42 in Salmonella infection." (PMID 36812247, 2023).
Salmonella Infections (continued). "In summary, we found that Salmonella infection decreased the acetylation level of CDC42 K153 through SIRT2, and the low acetylation level of CDC42 K153 could block the interaction between CDC42 and PAK4." (PMID 36812247, 2023). "We then tested whether Salmonella infection could mediate the migration/invasion ability of cancer cells and whether CDC42 K153 acetylation participates in regulating this process." (PMID 36812247, 2023). "Importantly, the unidirectional regulation of MEK1/2 activity by Cdc42 was recapitulated upon both Salmonella infection and SopB overexpression." (PMID 36717589, 2023). "In this regard, studies have shown that in healthy colon tissue, CDC42 and its co-expressed genes are related to various KEGG pathways such as 'endocytosis', 'Salmonella infection', 'adherens junction', and others." (PMID 37365287, 2023). "In the Salmonella infection pathway, FOS is also a downstream mediator of the Rho family GTPases CDC42." (PMID 27474500, 2016). "In the Salmonella infection pathway, MAPK14 is a downstream mediator of the Rho family GTPases CDC42." (PMID 27474500, 2016). "In HEK293T cells with stable knockdown of SIRT2, Salmonella infection failed to reduce K153 acetylation and the binding of CDC42 to PAK4 was restored." (PMID 36812247, 2023). "In this study, although the acetylation of CDC42 K153 is recognized as a key step regulating the interaction between CDC42 and PAK4, other Salmonella infection-induced PTMs of CDC42 may also change the affinity between these two proteins." (PMID 36812247, 2023). "Interestingly, our SILAC results revealed that several members of the Rho GTPases network (CDC42, FAS, and MYC) underwent dynamic acetylation following Salmonella infection." (PMID 36812247, 2023). "Immunohistochemistry (IHC) showed that the acetylation level of CDC42 K153 in tumors with Salmonella infection was lower than that in tumors without infection." (PMID 36812247, 2023). "Our results showed that the acetylation of CDC42 has little effect on the binding of PAK1, but the regulatory mechanism in the AOM/DSS induced CRC model with Salmonella infection is highly complicated, so other factors might enhance phosphorylation of PAK1 besides CDC42." (PMID 36812247, 2023). "Our data do not support the mentioned hypothesis since intestinal Salmonella infection led to significantly anti-correlated expression of miR-29a and CAV2 on transcriptional as well as translational level, while an obvious linkage to CDC42 was neither detected in vivo nor in vitro." (PMID 23826261, 2013).
cyst (11 papers, 2014 to 2024). A sac-like closed membranous structure that may be empty or contain fluid or amorphous material. "Defects in cyst integrity have been described in mutant alleles of several trafficking or membrane-associated molecules, including Rab11, Sec5, and Cdc42." (PMID 32117961, 2020). "Cdc42 has been reported to promote cilia formation through the localization of the exocyst complex to the cilia base and kidney-specific cdc42 deletion is associated with cyst formation." (PMID 32663194, 2020). "Cdc42 silencing caused dilated spherical lumina; however, Rab35 knock-down yielded the most striking phenotype, causing the appearance of epithelial tubes (white arrowhead) and large cyst-like structures (yellow arrowhead) compared with control (Luciferase, siLuc)." (PMID 34328499, 2021). "When exogenous PIP2 is added to the basal membrane, Cdc42 and ZO-1, along with other tight junction proteins, relocalize to the basal sites of the cyst." (PMID 37155619, 2023). "Our data demonstrated that Shp2-E76G expression reduced Cdc42 activity, leading to multi-lumen cyst formation as seen in MDCK with Cdc42 inactivation." (PMID 26783207, 2016). "We confirm the relevance of this disease mechanism by showing that two different RAC1/CDC42 activators mitigate the pronephric cyst phenotype in zebrafish." (PMID 26905694, 2016). "We provide evidence that MST3 controls MDCK cyst formation through apoptosis and Cdc42 regulation." (PMID 37155619, 2023). "At the beginning of cyst formation (Day 1), Cdc42 localized at cell-cell and cell-ECM contacts; thereafter (Days 2–5), the majority of Cdc42 localized at apical contacts, delimiting the newly formed lumen." (PMID 37155619, 2023). "While Par3 localized to the tight junctions, other apical proteins such as Crumbs3, Cdc42 and aPKC were not correctly localized in the centre of the two-cell-stage cyst in Rab35Q67L-Mito-expressing cells." (PMID 27040773, 2016). "Of note, Cdc42 activity in Shp2-E76G cyst was not increased by U0126 and Y27632 treatment." (PMID 26783207, 2016).
lung adenocarcinoma (11 papers, 2012 to 2023). A carcinoma that arises from the lung and is characterized by the presence of malignant glandular epithelial cells. "Furthermore, we investigated whether pHLIP-miR-29a inhibits other target proteins including LASP1 and CDC42 associated with lung adenocarcinoma cell proliferation." (PMID 37684602, 2023). "To this aim, we transfected StarD13-depleted lung adenocarcinoma cells with a constitutively active RhoA or a constitutively active Cdc42 construct." (PMID 32900380, 2020). "To further study the potential clinical relevance of our findings from mouse model, we analyzed a set of 84 lung adenocarcinoma for expression patterns of CDC42 and SP-A, a marker for human AECII35." (PMID 28871124, 2017). "In accordance with its tumor promoting role in alveolar tumor formation, CDC42 expression is positively correlated with alveolar marker surfactant protein A1 (SP-A) expression in human lung adenocarcinoma patients." (PMID 28871124, 2017). "In addition to CEACAM6, mir-29a also targets LASP1 and CDC42 and regulates proliferation, migration, and invasion of lung adenocarcinoma cells." (PMID 37684602, 2023). "Finally, and for the first time, we demonstrate a role for StarD13 in invadopodia formation, matrix degradation and invasion of lung adenocarcinoma cells by regulating Cdc42." (PMID 32900380, 2020). "In addition, Cdc42 depletion inhibited invasion in control lung adenocarcinoma cells." (PMID 32900380, 2020). "We have proved the over-expression of CDC42 and ARHGEER9 factors in lung adenocarcinoma." (PMID 23874428, 2013). "Overall, our data reveal an important physiological role for S100-A15 in comprehending the proliferative, metastatic, and invasive properties of lung adenocarcinoma which may be orchestrated by CTNNB1 with the involvement of ZEB1, CDC42, HSP90AA1, PCNA and BST2." (PMID 28498804, 2017).
pulmonary fibrosis (11 papers, 2020 to 2025). Chronic progressive interstitial lung disorder characterized by the replacement of the lung tissue by connective tissue, leading to progressive dyspnea, respiratory failure, or right heart failure. "The loss of Cdc42 function in alqaveolar stem cells (AT2 cells) leads to progressive lung fibrosis." (PMID 35091537, 2022). "Reduced levels of CDC42 in alveolar stem cells contributed to progressive pulmonary fibrosis." (PMID 39487595, 2024). "For example, lungs lacking the small Rho GTPase Cdc42 develop pulmonary fibrosis that is caused by mechanical cytoskeletal tension on alveolar epithelial cells." (PMID 38324689, 2024). "Furthermore, in Cdc42-null mice, the loss of Cdc42 functions in AT2 cells leads to progressive lung fibrosis in post-PNX lungs, with a pattern similar to IPF (from the periphery to the center of the lung)." (PMID 34208586, 2021). "These cells also appear similar to the intermediate cells derived from AEC2s of CDC42 null mice after pneumonectomy which show a progressive lung fibrosis, suggesting persistence of transitional cells may mediate lung fibrosis." (PMID 33900491, 2021). "In addition, mouse models showed that conditional knockout of Cdc42 in AEC2s could lead to progressive pulmonary fibrosis." (PMID 39346776, 2024).
schizophrenia (11 papers, 2011 to 2022). A major psychotic disorder characterized by abnormalities in the perception or expression of reality. "Abnormal Cdc42 signaling has been linked to cognitive impairments and aberrant spine remodeling in certain psychiatric and neurodegenerative disorders, including schizophrenia and Alzheimer's disease." (PMID 35415964, 2022). "In addition, miR-185 has two validated targets (RhoA, Cdc42), both of which have been associated with altered expression levels in schizophrenia." (PMID 24367288, 2013). "It has also been found that the effects of ZDHHC8 are at least partially mediated by the Cdc42-dependent modulation of Akt/Gsk3b signalling, which is consistent with the increasingly supported association between dysregulated Akt/Cdc42 signalling dysregulation and schizophrenia in humans." (PMID 35457231, 2022). "For example, decreased Cdc42 activity impairs remote memory recall and contributes to the reduction in dendritic spines in layer 3 pyramidal neurons in schizophrenia." (PMID 35415964, 2022). "Genes and proteins that have been linked to the regulation of spine morphology and development, such as Neuregulin-1 and ErbB4 or Cdc42, show aberrant expression or signaling in schizophrenia patients." (PMID 35496908, 2022). "Cell division cycle 42 (CDC42) levels and dendritic spine density have also been observed to decrease in patients with schizophrenia." (PMID 34512781, 2021). "p21-activated kinase 1 (PAK1) regulates both the actin cytoskeleton and dendritic spine density, and is a downstream effector of both kalirin and CDC42, both of which have altered expression in schizophrenia." (PMID 23613712, 2013). "Moreover, the finding that decreased Cdc42 signaling is responsible for decreased spine density and cognitive dysfunction in schizophrenia further supports the role of Cdc42 in regulating spine and behavior." (PMID 35415964, 2022). "This reduced expression of CDC42 may contribute to the decreased density of dendritic spines and cognitive dysfunction observed in schizophrenia." (PMID 30341976, 2018). "CDC42 mRNA is downregulated in the dorsolateral prefrontal cortex of schizophrenia patients." (PMID 30341976, 2018). "mRNA for the kalirin-7 isoform and for CDC42 have been reported to be reduced in schizophrenia." (PMID 23613712, 2013). "Prior findings of altered kalirin protein levels and kalirin and Cdc42 mRNA expression in schizophrenia were not layer specific, leading us to evaluate whole gray matter." (PMID 23613712, 2013).